GZMB (granzyme B)
Diseases named in the same sentence as GZMB in open-access papers (continued):
Sharing a sentence is not in itself a finding about the gene and the disease.
cervical squamous cell carcinoma (2 papers, 2021 to 2022). A squamous cell carcinoma arising from the cervical epithelium. "The prognostic correlation analysis of cervical squamous cell carcinoma and endocervical adenocarcinoma (CESC) showed that high expression of GZMB was negatively correlated with survival." (PMID 36497244, 2022).
chordoma (2 papers, 2021 to 2023). Chordomas are rare malignant tumors arising from embryonic remnants of the notochord in axial skeleton. "The examination of NKT and NK cells in chordoma revealed their elevated cytotoxicity, which was distinguished by the presence of PRF1, GZMB and GNLY." (PMID 37784253, 2023). "An obvious increase was observed in the secretion of both granzyme B and perforin in B7-H3-retargeted CAR-T cells forty-eight hours after co-culture with chordoma cells at a 2:1 E:T ratio." (PMID 34868903, 2021).
chronic lymphocytic leukemia (2 papers, 2019 to 2025). "Single-agent trabectedin induced mRNA expression of IFNG and GZMB in CD8+ T cells from patients with chronic lymphocytic leukemia treated in vitro, which aligns with our findings in NK cells." (PMID 39777457, 2025). "Moreover, upon IL-21 stimulation, B cells are capable of producing granzyme B. In chronic lymphocytic leukemia (CLL), IL-21–stimulated leukemic B cells can kill non stimulated ones." (PMID 31086070, 2019).
colorectal tumor (2 papers, 2023). "Studies in human pancreatic and colorectal tumours conducted by Gastpar R and his colleagues suggested that NK cells cultured with tumour-derived Hsp70-positive exosomes were induced to liberate granzyme B that activated apoptosis." (PMID 37875600, 2023).
Depression (2 papers, 2015 to 2024). "Depression has been associated with sympathetic nervous system activation and release of neuropeptides (epinephrine, neuropeptide Y), which has a suppressive effect on NK cell activity by reducing levels of perforin and granzyme B." (PMID 25663421, 2015).
endothelial dysfunction (2 papers, 2025). In vascular diseases, endothelial dysfunction is a systemic pathological state of the endothelium (the inner lining of blood vessels) and can be broadly defined as an imbalance between vasodilating and vasoconstricting substances produced by (or acting on) the endothelium. "Conversely, these endothelial dysfunction-related markers correlated negatively with the frequency of Ki-67+GzmB+ and Ki-67+CLA+ CD4+ T-cells." (PMID 40595657, 2025).
epidermolysis bullosa acquisita (2 papers, 2018 to 2023). "In human bullous pemphigoid, dermatitis herpetiformis, and epidermolysis bullosa acquisita, GzmB was elevated at the DEJ when compared to healthy samples, while α6/β4 integrin, collagen VII, and collagen XVII were reduced or absent in the area of blistering." (PMID 29946113, 2018).
esophageal carcinoma (2 papers, 2019 to 2021). A primary or metastatic malignant neoplasm involving the esophagus. "The chemokines CCL4 and CCL20 have been shown to recruit subsets of T cells in esophageal carcinoma, where CCL4 expression was correlated with the expression of CD8 and GZMB." (PMID 30451357, 2019).
Ewing sarcoma (2 papers, 2012). A small round cell tumor that lacks morphologic, immunohistochemical, and electron microscopic evidence of neuroectodermal differentiation. "We conclude that the level of GD2 expression in many Ewing sarcomas is sufficient to specifically activate T cells and trigger cytolysis by granzyme B secretion via GD2-specific CARs." (PMID 22374462, 2012). "We previously demonstrated natural killer cell-mediated apoptosis induction in Ewing sarcoma cells to be largely dependent on the perforin/granzyme B-mediated granule exocytosis pathway rather than on caspase-dependent death receptor pathways." (PMID 22587892, 2012).
fungal infections (2 papers, 2021 to 2025). "MAIT cells play a crucial role in controlling bacterial and fungal infections through their production of cytokines, including IFN-γ, TNF-α, and IL-17, as well as cytotoxic molecules such as Granzyme B and Perforin." (PMID 40025566, 2025).
helminth infections (2 papers, 2013 to 2024). "For example, Granzyme B has been found to be correlated with villus damage in helminth infections." (PMID 24340121, 2013). "However, this may be because Tg itself can inhibit lymphocyte degranulation and GZMB-mediated apoptosis of infected cells, or the fact that the impact of worm infection on GZMB is unclear." (PMID 38950025, 2024).
hepatitis B (2 papers, 2011 to 2022). "This frequency is comparable to the 10% of granzyme B+ cells among the CD8 T cells in the liver of patients with hepatitis B, but it can reach 40% in hepatitis B patients that have an autoimmune disease characterized by T cell hyperreactivity." (PMID 24212939, 2011).
hyperandrogenemia (2 papers, 2019 to 2022). "Further results showed that granzyme-B was higher in PCOS patients which was positively correlated with hyperandrogenemia." (PMID 36518256, 2022).
Hypercalcemia (2 papers, 2017 to 2023). An abnormally increased calcium concentration in the blood. "We have previously shown that Tax transgenic mice (under the Granzyme B promoter) develop bone loss and hypercalcemia by 9 months of age." (PMID 29050201, 2017). "GzmB-Tax transgenic mice were observed to have hypercalcemia and osteolytic bone metastases, which frequently occur in patients with ATL." (PMID 37511495, 2023). "Transgenic mice expressing HBZ under the control of the granzyme B promoter (Gzmb-HBZ) develop lymphoproliferative diseases such as tumors, splenomegaly, abnormal white blood cell numbers, and hypercalcemia." (PMID 37511495, 2023). "We found that in addition to Granzyme B and HBZ, PTHrP was significantly increased in T cells isolated from Gzmb-HBZ mice, providing the first in vivo evidence that HBZ could mediate hypercalcemia through enhanced PTHrP expression." (PMID 29050201, 2017). "We have previously reported that Tax transgenic mice under the Granzyme B promoter model many aspects of human ATL and that osteoclast inhibitors could inhibit the hypercalcemia and osteolytic bone lesions in these mice." (PMID 29050201, 2017).
injury (2 papers, 2020 to 2024). Damage inflicted on the body as the direct or indirect result of an external force, with or without disruption of structural continuity. "A previous study showed that GZMB deficiency increased morbidity and mortality in bleomycin-induced acute lung injury model in mice." (PMID 32856055, 2020). "MiR-378a-5p inhibits GZMB expression in children with acetaminophen overdose-induced liver injury." (PMID 39176087, 2024).
intrahepatic cholangiocarcinoma (2 papers, 2024). A carcinoma that arises from the intrahepatic bile duct epithelium in any site of the intrahepatic biliary tree. "Our study unveils an interaction between granzyme B+ B cells and intrahepatic cholangiocarcinoma, opening up potential avenues for the development of novel therapeutic strategies against this disease." (PMID 38386050, 2024). "Similarly, it was recently shown that GZMB+ B cells were able to infiltrate liver grafts in patients with intrahepatic cholangiocarcinoma." (PMID 39120317, 2024).
Lewis lung carcinoma (2 papers, 2023 to 2024). "In intracellular Notch1-expressing mice, an increase in cytotoxicity of CD8+ T cells mediated by IFN-γ and granzyme B production was observed, which delayed tumor growth in the syngeneic murine Lewis lung carcinoma model." (PMID 39209451, 2024).
liver cirrhosis (2 papers, 2022 to 2025). "When compared to healthy controls, only 7 DEGs, including 6 up-DEGs (TYMP, TYROBP, TGFBI, LILRA2, GNLY, and GZMB) and 1 down-DEG (CD14) were common to CHB, liver cirrhosis, and HCC." (PMID 35265561, 2022).
Lymphadenopathy (2 papers, 2020). Enlargement (swelling) of a lymph node. "Regarding the molecules secreted by these cells, IL-1β+ and TNF-α+ were found to be the most highly expressed, mainly in individuals with lymphadenopathy, followed by perforin+ and granzyme B+." (PMID 32766167, 2020).
mastocytoma (2 papers, 2014 to 2024). A localized tumor composed of sheets of mast cells without atypia. "Next, the killing activity of CTLs, which is at least partially mediated by GZMB, was assessed in the presence or absence of Ap, using a CD3 antibody (OKT3) loaded P815 mastocytoma target and effector CTL co-culture system." (PMID 38720895, 2024).
meningioma (2 papers, 2023 to 2024). A generally slow growing tumor attached to the dura mater. "We have found a positive and significant correlation between the expression of 5-LOX and GzmB in PBTs, both at RNA and protein levels also suggesting their association with the progression from meningioma to astrocytoma and GBMs." (PMID 38816839, 2024). "Correlation matrix analysis revealed that 5-LOX and GzmB expression were associated in both meningiomas and GBMs, whereas 5-LOX expression was significantly and positively correlated to TG2 in both meningioma and astrocytoma cohorts." (PMID 38816839, 2024). "In line with CD8, the expression of GzmB was significantly higher in the meningioma cohort than in GBMs (p < 0.001) and than in astrocytoma tumours (p < 0.01)." (PMID 38816839, 2024).
myositis (2 papers, 2018 to 2023). "Furthermore, granzyme B cleavage sites have been identified in autoantigens, such as FHL1 and HisRS, targeted in autoimmune disorders, including myositis." (PMID 30157932, 2018).
nematode infection (2 papers, 2022 to 2024). "GZMB is also upregulated during nematode infections, although its precise role (harmful/beneficial to the host) also remains controversial." (PMID 38950025, 2024). "The resistance of cattle to nematode infection and innate immunity requires the participation of GZMB." (PMID 35646088, 2022).
oral cancer (2 papers, 2014 to 2021). "Moreover, the CD127loCCR7−CD45RA−CD8+ T cell or CCR7−CD45RA+CD8+ T cell subsets exhibited a significantly higher activity in either absolute granzyme B producing levels or relative frequencies of granzyme B-expressing cells occur in oral cancer patients." (PMID 24465587, 2014).
pancreatitis (2 papers, 2023 to 2025). Inflammation of the pancreas. "Also, pathological examination of ICI-related pancreatitis using multiplex fluorescence immunohistochemistry demonstrated infiltration of predominantly CD8 positive T lymphocytes contained abundant granzyme B into the pancreatic parenchyma." (PMID 40799644, 2025).
panniculitis (2 papers, 2021 to 2025). Inflammation of the subcutaneous adipose tissue. "Due to its nonspecific presentation and histological overlap with panniculitis, early diagnosis requires a high index of suspicion, prompt biopsy of nodular lesions, and immunophenotyping using markers such as CD2, CD3, CD8, granzyme B, and TIA-1." (PMID 40709991, 2025).
polymyositis (2 papers, 2022 to 2023). A rare idiopathic inflammatory myopathy characterized by symmetric proximal muscle weakness and elevated muscle enzymes. "Analysis of muscle biopsies from polymyositis patients showed that CD8+ T cells are the principal source of necrotic myofibers throughout the expression of cytotoxic effector molecules including perforin 1 and granzyme B." (PMID 36538023, 2023).
pulmonary arterial hypertension (2 papers, 2017 to 2018). Pulmonary arterial hypertension (PAH) is a group of diseases characterized by mean pulmonary artery pressure >20 mmHg and elevated pulmonary arterial resistance leading to right heart failure. "Intersectin-1s (ITSN) deficiency and expression of a biologically active ITSN fragment, result of granzyme B cleavage under inflammatory conditions associated with pulmonary arterial hypertension (PAH), are characteristics of lung tissue of human and animal models of PAH." (PMID 30333761, 2018). "In inflammatory conditions such as pulmonary artery hypertension, ITSN-1s full length protein is cleaved by granzyme B into EHITSN and SH3A-EITSN fragments." (PMID 28874189, 2017).
renal fibrosis (2 papers, 2015 to 2025). A final common manifestation of a wide variety of chronic kidney diseases characterized by glomerulosclerosis and tubulointerstitial fibrosis. "In the UIRI-induced renal fibrosis model, Western blot and qRT-PCR analyses revealed significant upregulation of GzmB in fibrotic kidneys compared to controls." (PMID 41244830, 2025). "In this study, we observed an upregulation of GZMB expression in both in vivo renal fibrosis models and HK-2 cells treated with TGF-β." (PMID 41244830, 2025). "GZMB was upregulated in various mouse models of renal fibrosis as well as in TGF-β-stimulated HK-2 cells." (PMID 41244830, 2025). "This study confirmed that GZMB promotes the process of renal fibrosis by inducing renal tubular cell injury and p-EMT." (PMID 41244830, 2025). "To investigate the role of GZMB in renal fibrosis, we established multiple murine models of kidney fibrosis." (PMID 41244830, 2025). "Since NCAM can be also expressed by natural killer (NK) cells of the innate immune system, double NCAM/granzyme B immunostaining was performed to clarify their relationship in incipient renal fibrosis." (PMID 26327314, 2015). "In this study, both in vivo renal fibrosis models and HK-2 cells treated with TGF-β confirmed that the expression of GZMB was significantly upregulated during disease progression." (PMID 41244830, 2025). "To further explore the effect of fibrosis on the expression of GZMB in vitro, we stimulated human proximal renal tubular (HK-2) cells with TGF-β, a key mediator of renal fibrosis, to induce the occurrence of fibrosis." (PMID 41244830, 2025). "To elucidate the therapeutic mechanisms of NM in renal fibrosis, we integrated in vivo unilateral ischemia-reperfusion injury (UIRI) models with in vitro experiments using human proximal tubular epithelial (HK-2) cells stimulated by TGF-β or GZMB." (PMID 41244830, 2025).
secondary progressive multiple sclerosis (2 papers, 2024). A multiple sclerosis with a clinical course characterized by a progressive accumulation of neurological disability, independent of relapses, following an initial relapsing-remitting (RR) phase. "Using our longitudinal analysis, which involved a 6-monthly collection of serum samples, we were able to show that changes in granzyme B and immune-associated miRNA patterns mark the conversion to secondary progressive multiple sclerosis." (PMID 38978729, 2024). "A peak in circulating granzyme B levels was observed around the conversion from relapsing–remitting to secondary progressive multiple sclerosis." (PMID 38978729, 2024). "The opposite is true for secondary progressive multiple sclerosis (SPMS), where CNS-resident EOMES+GZMB+NR4A2+CD4+ T cells correlate with active progressive disease." (PMID 39025930, 2024).
Shock (2 papers, 2012 to 2025). The state in which profound and widespread reduction of effective tissue perfusion leads first to reversible, and then if prolonged, to irreversible cellular injury. "Notably, members of our group are currently pursuing GZMB and MMP8 as novel therapeutic targets in septic shock, and younger age was previously linked to higher mortality in pediatric septic shock." (PMID 23025259, 2012).
skin aging (2 papers, 2015 to 2021). The gradual irreversible changes in structure of skin that occur as a result of the passage of time.. "Furthermore, a role of GzmB has emerged in dermatological indications with studies implicating extracellular GzmB activity in diet-induced models of skin aging and impaired wound healing." (PMID 25495009, 2015).
systemic juvenile idiopathic arthritis (2 papers, 2008 to 2024). "In patients with systemic juvenile idiopathic arthritis, high levels of IL-6 inhibit the cytotoxicity of NK cells and down-regulate the expression of granzyme B and perforin." (PMID 39346912, 2024). "In the present study we therefore hypothesized that defective apoptosis in patients with systemic-onset JIA could be due to polymorphisms in the genes PRF1, GZMB, UNC13D, or Rab27a." (PMID 18311812, 2008). "In conclusion, we could not detect an association between SNPs in PRF1, GZMB, UN13D, or Rab27a and an increased risk of susceptibility to systemic-onset JIA." (PMID 18311812, 2008).
systemic sclerosis (2 papers, 2023 to 2025). A chronic disorder, possibly autoimmune, marked by excessive production of collagen which results in hardening and thickening of body tissues. "Evidence suggests that GzmB is elevated in systemic sclerosis and may be associated with certain disease complications." (PMID 36830757, 2023). "Multiple studies have documented GZMB downregulation in AS, SLE, and systemic sclerosis, concomitant with impaired cytotoxic function of CD56dim NK cells." (PMID 41323479, 2025).
Thrombocytopenia (2 papers, 2018 to 2024). A reduction in the number of circulating thrombocytes. "In fact, whereas thrombocytopenia did not affect intratumor granzyme B level in B16F1 tumors, it increased it in AT-3 tumors." (PMID 38493157, 2024).
thyroid (2 papers, 2025). "In a mouse model, administration of anti-PD1 antibodies combined with thyroid globulin induced thyroid-related immune ADEs, with CD4+ T cells expressing granzyme B directly damaging thyroid follicular cells." (PMID 40894206, 2025). "While a role for IL-21 in ICI-T1DM has not been described, we showed in mice and humans with ICI-thyroiditis that IL-21 from CD4+ cells could augment effector molecules (IFN-γ, granzyme B) and chemokine receptors on thyrotoxic CD8+ T cells." (PMID 40626363, 2025).
typhoid fever (2 papers, 2017 to 2024). A bacterial infectious disorder contracted by consumption of food or drink contaminated with Salmonella typhi. "In the present study, we demonstrate that plasma concentrations of extracellular granzyme A and granzyme B were both elevated in typhoid fever at day of admission." (PMID 28749963, 2017). "The present study showed an increase in extracellular levels of granzyme A and B in patients with typhoid fever compared to controls, and lower levels of granzyme B in patients at day of discharge compared to admission." (PMID 28749963, 2017). "Importantly, our work establishes a new paradigm in which a perforin-independent role of GzmA and GzmB mediates protection against enteric Salmonella infection, and provides a rational explanation for the high levels of extracellular GzmA seen in patients with typhoid fever." (PMID 39137883, 2024). "In line with the measured extracellular granzyme levels, lymphocytes of typhoid fever patients had a higher percentage of cells expressing intracellular granzyme A and granzyme B than controls, although the increase in cell numbers was not significant." (PMID 28749963, 2017). "Peripheral blood mononuclear cells of typhoid fever patients had a higher percentage of lymphocytic cells expressing intracellular granzyme A and granzyme B, but not granzyme K, compared to controls." (PMID 28749963, 2017).
ulcer (2 papers, 2024). "In contrast with the role of CD4+ Th1 cells in controlling Leishmania infection, CD8+ T cells and NK cells as well as a high expression of IL-1β, IL-17, and Granzyme B (GzmB) at the lesion site are associated with pathology and ulcer development." (PMID 39599571, 2024). "As both the production of cytokines at the lesion site and the size of the ulcers were quite variable, to better evaluate the association between IL-1β, IL-17, and GzmB with lesion size, we compared these cytokine levels in the supernatants of skin biopsies with the size of the ulcers." (PMID 38535542, 2024). "Patients presenting an ulcer size larger than 206 mm2 displayed significantly higher levels of IL-1β, IL-17, and GzmB in lesion cultures compared to patients whose ulcers were smaller than 206 mm2." (PMID 38535542, 2024).